BRAF (B-Raf proto-oncogene, serine/threonine kinase)
Diseases named in the same sentence as BRAF in open-access papers (continued):
Sharing a sentence is not in itself a finding about the gene and the disease.
melanoma (continued). "An increased risk of death from melanoma (five‐year disease‐specific survival, DSS; HR, 1.9; 95% CI, 1.21–3.10; P = 0.046) and poor OS (HR, 2.0; 95% CI, 1.28–2.98; P = 0.01) were observed in the NF1 subtype compared to the reference group, BRAF." (PMID 28267273, 2017). "However, as in melanoma, drug combinations appear to yield increased efficacy in V600E BRAF-mutant NSCLC, with dabrafenib plus trametinib, an MEK inhibitor, showing an impressive RR of 63% and a PFS of 9.7 months." (PMID 29225694, 2017). "Immunological mechanisms may also be responsible for early reports of clinical benefits from combination therapy with the anti-PD-L1 antibody atezolizumab and the MEK inhibitor cobimetinib in patients with BRAFV600E mutant and BRAF wild-type melanoma." (PMID 29100459, 2017). "Taken together these data suggest that the increases in total MET and GAB1 may prime BRAF mutant melanoma cells for HGF-mediated rescue." (PMID 28147313, 2017). "Moreover, it has been recently reported that STAG2 inactivation confers resistance to BRAF inhibitors in melanoma." (PMID 28430577, 2017). "A similar pattern was observed in vivo: Tumour biopsies from nine stage IV melanoma patients, treated with the BRAF inhibitors vemurafenib or dabrafenib, showed increased PS102-YB-1 levels after the development of drug resistance compared to the tumours before the start of treatment." (PMID 28415756, 2017). "In addition, stimulation of TAMs by BRAF/MEK inhibitors also plays a role in promoting melanoma growth." (PMID 29050218, 2017). "A 76–year-old woman was diagnosed in October 2012 with an anal canal non-mutated BRAF melanoma (Mucosal Lentiginous Melanoma in vertical growth phase, Breslow thickness 20 mm, presence of ulceration, pT4bN0M0, stage IIC)." (PMID 28716106, 2017). "To validate whether the RhoJ-PAK signaling network influenced the growth of BRAF mutant tumors, we determined whether PAK inhibitors could block the growth of BRAF mutant autochthonous mouse melanomas during early phases of development." (PMID 28753606, 2017). "Although biological and clinical implication of the frequency of mutant alleles of BRAF in melanomas are currently under investigation, no data are available concerning the variation of M%NRAS." (PMID 28668077, 2017). "In melanoma, BRAF mutations account for roughly 40–50% of all cases and is most common in so-called non-chronic sun damage melanomas." (PMID 28915798, 2017). "No studies of feedback loop activation induced by refametinib have been published; however, previous studies of MEK/MAPK inhibition in BRAF-inhibitor resistant melanoma cells show that MEK inhibitors can activate AKT signalling as an escape mechanism through increased MEK/RAF activation." (PMID 29156708, 2017). "The melanomas used here include BRAF-mutant cells (HT144, 451Lu and MB2309), NRAS-mutated cells (WM852c, SKMEL-30, Hs852T), NF-null cells (Hs852T), or wild-type cells for the common mutations in BRAF, NRAS, or NF1 (MB2141)." (PMID 27086916, 2017). "Responses in patients with BRAF‐WT melanoma indicate that the development of more specific pan‐RAF inhibitors may provide a feasible therapeutic avenue for these patients." (PMID 28719152, 2017). "Inhibition of MYC overcomes drug resistance in BRAF-driven melanoma and other human cancers." (PMID 28152508, 2017). "Interestingly, a mobility shift was previously reported in an NRASmut melanoma cell line treated with a BRAF inhibitor and was attributed to a phosphorylation event that was both MEK pathway-dependent and independent." (PMID 27999210, 2017). "Interestingly, the inhibition of PDK1 with AZD7545 specifically suppressed growth of BRAF-mutant and BRAF inhibitor resistant melanoma cells." (PMID 28595656, 2017).
melanoma (continued). "These preliminary findings suggest that combining anti-CSPG4 antibodies with pathway inhibitors may enhance the restricted success of BRAF inhibitors in melanoma." (PMID 29375561, 2017). "We evaluated our approach using 10-fold cross-validation and found that our model exhibits significant power for predicting both synergy (AUC = 0.8663, Accuracy = 0.8213) and genotype-selective efficacy (AUC = 0.8809, Accuracy = 0.8230) in context of BRAF melanomas." (PMID 28085880, 2017). "However, BRAF-targeted therapies have shown diverse clinical responses to different activating BRAF alterations in melanoma and other cancers." (PMID 29156677, 2017). "It is tempting to speculate that the targeting of PDKs in combination with BRAF inhibitors could be a promising strategy to more efficiently hit melanoma cells or to delay the onset of drug resistance." (PMID 28595656, 2017). "Importantly, all three EPE-resistant melanomas selected were also resistant to BRAF inhibition, indicating a common ERK related mechanism of resistance." (PMID 29180761, 2017). "In this study we assessed the potential of non-invasive imaging approaches (photoacoustic imaging (PAI) and magnetic resonance imaging (MRI)) to detect melanin induction in SKMEL28 human melanoma cells, following inhibition of Hsp90 and BRAF signaling using 17-AAG and vemurafenib, respectively." (PMID 28811486, 2017). "Given the central role of gene methylation in tumorigenesis, EZH2 and BRAF may cooperate to promote the initiation and progression of melanoma." (PMID 29202777, 2017). "Similarly, BRAF V600E melanoma patients concurrent with LKB1 low expression are more likely to have lymph node metastases and related to the MMP-2 high expression." (PMID 29371951, 2017). "In another study, though BRAF-mutant CRCs were more sensitive to Dabrafenib (BRAF inhibitor) and Trametinib (MEK inhibitor) combination therapy than to Dabrafenib (BRAF inhibitor) single agent therapy, the response seen was less impressive than what has been observed in melanoma." (PMID 28640835, 2017). "However, some melanomas, despite harbouring a mutant BRAF gene, express higher levels of additional oncogenic drivers that confer intrinsic MAPK inhibitor resistance." (PMID 28606996, 2017). "However, many genetic resistance mechanisms converge on reactivation of the intended protein or pathway target, as in the case of the MAPK pathway in BRAF mutant melanoma or CRC." (PMID 28431544, 2017). "What is almost certain is that like BRAF-activating mutations, MEK-activating mutations combined with loss of tumor suppressors in melanocytes are likely to produce melanoma and may require special considerations in the clinic to optimize patient care." (PMID 28263969, 2017). "However, with the exception of BRAF‐mutant melanomas, the clinical therapeutic efficacy of MEK inhibitors as single agent for other cancer types has been underwhelming." (PMID 28632938, 2017). "Monotherapy with BRAFi and combined therapy with BRAFi and MEKi possess remarkable clinical activity in patients with metastatic BRAF-mutant melanoma - yielding objective response rates of 50–60% and of 65–75%, respectively - and significantly prolong progression-free and overall survival." (PMID 29371923, 2017). "In many melanomas, PGC1α expression is low due to suppression of MITF by oncogenic BRAF mutations." (PMID 29137417, 2017). "Furthermore previous reports have suggested that the combination of BRAF inhibitors with paclitaxel represents a promising therapeutic approach for overcoming resistance in BRAF melanomas." (PMID 28085880, 2017). "Indeed, treatment of melanoma cell lines with conditioned medium derived from corresponding cell lines treated for 14 days with BRAF inhibitor, resulted in an increase in the phosphorylation of proteins recognized as PKC substrates." (PMID 28606996, 2017).
melanoma (continued). "In addition, BRAF-fusions occur in a wide range of adult malignancies including melanoma, gastric, thyroid, pancreatic, prostate and lung cancers." (PMID 29156677, 2017). "Given the high prevalence of WT BRAF in melanomas, we reasoned that melanomas with wild-type BRAF may exhibit a dependence on WEE1 epigenetic pathway activation for maintenance of the transformed phenotype." (PMID 29290954, 2017). "The patient's past medical history included desmoplastic BRAF mutation negative melanoma with metastatic disease to the face, liver, and trigeminal nerve." (PMID 28533998, 2017). "The authors of this study postulated that this blood biomarker would not represent an interesting early-stage marker for melanoma patients, despite the fact that BRAF mutations occur early in melanomagenesis." (PMID 28484715, 2017). "There are a series of mechanisms described that underlie the secondary resistance of BRAF-mutant melanomas that occur after BRAF inhibitor treatment, including NRAS mutations, aberrant BRAF splicing, BRAF amplifications, MAP2K1 (MEK1) mutations, PTEN and PIK3CA mutations, and COT1 overexpression." (PMID 27903987, 2017). "We cannot rule out the possibility that the determination of BRAF mutation in the original melanoma (which had been tested by immunohistochemistry) had been a false positive." (PMID 29285228, 2017). "In this paper, we use time‐lapse, live‐cell imaging, and single‐cell analysis to show that BRAF‐mutant melanoma cells exhibit time‐variable and heterogeneous phenotypes when exposed to MAPK pathway inhibitors such as vemurafenib, dabrafenib, and trametinib near the IC50 for cell killing." (PMID 28069687, 2017). "Enhanced processing of major effector caspases (caspase-3, caspase-7, caspase-8 and caspase-9) to their active forms and cleavage of PARP (a target of activated effector caspases) was observed at 48 hours following treatment of the BRAF V600E mutant (A375) human melanoma cell line with ixazomib." (PMID 27783987, 2016). "The combination increased the level of PARP cleavage relative to the DMSO or either treatment alone in all three relapsed melanoma patient samples tested, irrespective of the mutation status of BRAF or NRAS." (PMID 27829238, 2016). "Following treatment of BRAF wild-type melanoma cells with endoplasmic reticulum (ER) stress-inducing agents in vitro, autophagy is activated in line with its pro-survival role; however, when autophagy is inhibited exogenously, this leads to increased cell death." (PMID 27882308, 2016). "An 81-year-old man with past medical history including atrial fibrillation, coronary artery disease s/p myocardial infarction and ventricular tachycardia/ventricular fibrillation s/p automatic implantable cardioverter-defibrillator placement was diagnosed with metastatic BRAF wild-type melanoma." (PMID 27532025, 2016). "The antitumor activity of vemurafenib was observed in melanoma cell lines with BRAF V600E mutation, but not in wild-type melanomas." (PMID 27042173, 2016). "Another phase II study in which patients with BRAF wild-type melanoma are included indicated that the combined strategy of Ipilimumab + Nivolumab is far more effective than Ipilimumab monotherapy since the corresponding CR rate for two treatment group were 22% and 0%, respectively." (PMID 27764796, 2016). "Further histological and clinical evidence showed that this hot spot mutation may be responsible for the early metastatic progression of BRAF mutant and BRAF wild-type melanoma." (PMID 27104658, 2016). "This was again consistent for all the melanoma cell lines tested irrespective of the mutation status of BRAF or NRAS." (PMID 27829238, 2016). "Melanoma cells are characterized by the expression of different cytokines, which may act as potential players in reducing the sensitivity to BRAF inhibition." (PMID 26684239, 2016).
melanoma (continued). "Interestingly, the clinical inhibitor of the common BRAF V600E/D variants, Vemurafenib (PLX-4032), which is currently used to treat melanoma patients with BRAF V600E/D-mutated metastatic melanomas, decreased CD70 expression in human CD70+ melanoma cell lines." (PMID 26828592, 2016). "When mutant BRAF melanoma cells were grown as 3D spheroids embedded in collagen and were stained with the LIVE/DEAD assay, SGI-1776 [10 μM] as a single agent reduced cell invasion and growth, and this was potentiated in the presence of the BRAF inhibitor PLX4720." (PMID 27448973, 2016). "Therefore, RASA1 consistently suppresses Ral-A activation in these BRAF activated melanoma cell lines." (PMID 26993606, 2016). "Furthermore, since oncogenic BRAF has been found to activate NFAT signaling in melanoma, and we found that CTHRC1 is expressed at high levels mainly in BRAF mutant melanoma cell lines, we examined the effect of BRAF inhibition on CTHRC1 expression." (PMID 26918341, 2016). "In the BRAF Inhibitor in Melanoma-3 (BRIM-3) trial, a phase 3 randomised open-label study comparing vemurafenib with dacarbazine in BRAF V600E- and BRAF V600K-mutant melanoma, 38 % of patients receiving vemurafenib required dose modifications because of toxicity." (PMID 26857260, 2016). "The ability of ixazomib to induce apoptosis of BRAF wild-type human melanoma cells was evaluated." (PMID 27783987, 2016). "For instance, in melanoma, BRAF has a direct effect on autophagy regulation." (PMID 26735341, 2016). "Taken together, these results suggest that co-targeting of MEK1/2 and PI3K/mTOR, compared to BRAF and PI3K/mTOR dual blockade, is a more effective approach to rescue susceptibility to caspase-dependent apoptosis in melanoma cells with intrinsic cross-resistant phenotype." (PMID 26678033, 2016). "We provide scientific evidence that BRAF inhibitor resistance in the CNS may be mediated by melanoma cell extrinsic factors in the cerebrospinal fluid." (PMID 26414886, 2016). "While preclinical and clinical studies have shown that targeting BRAF (V600E) melanomas with the use of RAF-selective inhibitors results in initial tumor regression, responses to RAF inhibitors are transient, with acquired resistance triggering disease progression." (PMID 26999821, 2016). "Surprisingly, in our paper, we could also show that ERβ agonists were ineffective in reducing the proliferation of A375 and WM1552 (V600E BRAF-mutant) melanoma cells, expressing the ER isoform." (PMID 27833586, 2016). "Oncogenic BRAF in melanoma cells induces EMT through upregulation of Snail1 expression." (PMID 26517521, 2016). "On the other hand, ERβ agonists will not be able to reduce the proliferation of melanoma cells carrying the BRAF (V600E) mutation, which is associated with the overactivation of the MEK/ERK signaling cascade." (PMID 27833586, 2016). "Furthermore, oncogenic BRAF signaling has been shown to suppress E-cadherin expression and enhance melanoma cell invasion by inducing T-Box3 transcriptional repressor of E-cadherin expression." (PMID 26517521, 2016). "RasGAPs can inactivate wild type but not mutant Ras proteins and low level of RASA1 mRNA expression is associated with decreased overall survival of melanoma patients with a BRAF mutation; therefore, we addressed RASA1 function in melanoma cell lines containing BRAF mutations." (PMID 26993606, 2016). "Our findings suggest that SGI-1776 displays anti-melanoma effects in combination with BRAF inhibition in vivo; however, the inactivation of pathways such as PI3K and/or STAT3 may be necessary to obtain tumor regressions." (PMID 27448973, 2016). "Here, we implicate reactivation of TRIM16 as being partially required for tumor targeting by the combination therapy and suggest TRIM16 reactivation as an area for further investigation for melanoma treatment and a potential strategy for targeting BRAF wild-type and mutant melanomas." (PMID 27447557, 2016).
melanoma (continued). "Notably, pS6 has been identified as a marker of in vivo responsiveness to MEK inhibitors in BRAF-mutant melanoma." (PMID 27167191, 2016). "Several genes have been implicated in the development of melanoma: genes involved in the MAPK pathway (RAS and BRAF, the most frequent mutations), CDKN2A [a cyclin-dependent kinase (CDK) gene] genes that are associated with nevi and pigmentation traits, such as MTAP, MC1R, and TYR." (PMID 27833586, 2016). "We treated NRAS-mutant (YUGASP, SKMEL-2, SKMEL-103, and M318), BRAF-mutant (SKMEL-28 and A375), NF1-mutant/null (MeWo and YUTOGS), and NRAS/BRAF/NF1 wild-type (YUVON) melanoma cells with three DNA replication stress-inducing agents: aphidicolin, camptothecin, and hydroxyurea." (PMID 27608486, 2016). "Immune-checkpoint inhibition of either the CTLA-4 or PD-1 receptor can also improve the survival of patients with advanced melanoma, irrespective of the BRAF V600 mutation status." (PMID 27095081, 2016). "The mutational status for BRAF, NRAS and c-KIT was assessed in the melanoma samples." (PMID 26909610, 2016). "Further, in melanoma cells, both BRAF inhibition and combinatorial BRAF/MEK inhibition induced cytoprotective autophagy due to the activation of the endoplasmic reticulum (ER) stress response triggered by mutant BRAF binding to GRP78, a chaperone required for ER integrity." (PMID 27583134, 2016). "Clinical support for this comes from the observation that BRAF mutant melanoma patients treated with BRAF inhibitors show heterogeneity of response that may be explained by the presence of additional molecular alterations." (PMID 27397505, 2016). "Therefore, we determined the migratory ability of BRAF-mutated A375 and SK-MEL-28 melanoma cells treated with fisetin, sorafenib and their combination at relatively non-toxic doses." (PMID 26517521, 2016). "We tested whether the addition of digoxin would enhance responses of xenografted melanomas to BRAF inhibitor (dabrafenib) plus MEK inhibitor (trametinib)." (PMID 27545456, 2016). "In this communication we ask whether BRAFV600E melanomas share common adaptive responses to BRAF inhibition that can provide clinically relevant targets for drug combinations." (PMID 26673621, 2016). "Many groups have identified potential targets to enhance the cytotoxic effects of cancer therapeutics such as paclitaxel in lung cancer, PARP inhibitors in breast cancer, HDAC inhibitors in osteosarcoma, imatinib in CML, and BRAF inhibitors in colon cancer and melanoma among others." (PMID 27738492, 2016). "Driver mutations in BRAF and NRAS are the most prevalent oncogenic alterations in melanoma." (PMID 27095580, 2016). "In this context, we asked whether human NK cells can target melanoma cells that have acquired resistance to selective inhibitors targeting activating mutants of the B‐Raf kinase (BRAF inhibitors, BRAFi)." (PMID 26564811, 2016). "TGFβ levels are elevated in the plasma of melanoma patients (regardless of their exposure to BRAF inhibitors), and increases in expression are associated with progressive disease." (PMID 27835901, 2016). "Whereas melanomas arising on skin without chronic sun damage had frequent mutations in BRAF, those mutations were much less common in melanomas occurring on acral skin, mucosal surfaces, and chronically sun-damaged skin." (PMID 27031071, 2016). "Many studies have shown a role for BRAF signalling in the regulation of melanomas metabolism." (PMID 26907172, 2016). "On the basis of overlapping marker genes and proteins (for example, FN1 upregulation and MITF downregulation), we identified a biological similarity to a reported phenotypic switch in (BRAF inhibitor-naive) melanoma, as reported in a series of publications by Hoek, Dummer and colleagues." (PMID 27648299, 2016).